TDRD7 (tudor domain containing 7)
Description:
Component of specific cytoplasmic RNA granules involved in post-transcriptional regulation of specific genes: probably acts by binding to specific mRNAs and regulating their translation. Required for lens transparency during lens development, by regulating translation of genes such as CRYBB3 and HSPB1 in the developing lens. Also required during spermatogenesis.
Synonyms: Trap; PCTAIRE2BP; CATC4
Tractability: PROTAC: ubiquitination databases record sites on it; its protein half-life has been measured.
Target class: Methyl-lysine/arginine binding protein; Reader; Epigenetic regulator; Tudor domain
Gene: Protein-coding gene on chromosome 9 (97,412,069 to 97,496,125, forward strand). Ensembl gene ENSG00000196116.
Subcellular location: Cytoplasm
Subcellular location (Human Protein Atlas): Cytoplasmic bodies; Nucleoplasm
Gene Ontology:
Molecular function: mRNA binding; protein binding
Biological process: lens fiber cell differentiation; lens morphogenesis in camera-type eye; post-transcriptional regulation of gene expression; P granule organization; piRNA processing; spermatogenesis
Cellular component: cytoplasmic ribonucleoprotein granule; ribonucleoprotein granule; chromatoid body; cytoplasm; P granule; ribonucleoprotein complex
Genetic constraint (gnomAD): Loss-of-function variants: 44 observed, 108.5 expected, observed/expected ratio (o/e) 0.41, 90% interval 0.32 to 0.52. The upper end of that interval is the gene's LOEUF score, 0.52, which puts it in group 2 of 6, group 1 being the genes least tolerant of losing a copy. Missense variants: 1,160 observed, 1,381.9 expected, observed/expected ratio (o/e) 0.84, 90% interval 0.8 to 0.88. Synonymous variants: 424 observed, 482.07 expected, observed/expected ratio (o/e) 0.88, 90% interval 0.81 to 0.95.
Homologues: Orthologues: chimpanzee TDRD7 (99% identical), macaque TDRD7 (98% identical), pig TDRD7 (92% identical), rabbit TDRD7 (86% identical), guinea pig TDRD7 (85% identical), rat Tdrd7 (85% identical), mouse Tdrd7 (84% identical), tropical clawed frog tdrd7 (55% identical), zebrafish tdrd7b (48% identical), zebrafish tdrd7a (42% identical). Paralogues in human: TDRD15 (15% identical), TDRD6 (15% identical), TDRD1 (14% identical), TDRD5 (10% identical), TDRKH (7% identical), TDRD10 (4% identical).
Diseases named in the same sentence as TDRD7 in open-access papers:
TDRD7 is named in the same sentence as 17 diseases in open-access papers, as found by Europe PMC text mining. Sharing a sentence is not in itself a finding about the gene and the disease. The quoted sentences say what the papers report.
cataract (7 papers, 2014 to 2024). Partial or complete opacity of the crystalline lens of one or both eyes that decreases visual acuity and eventually results in blindness. "The protein encoded by TDRD7 is associated with lens development and is thought to be linked to cataracts, microphthalmia, and Peters abnormalities." (PMID 39408566, 2024). "Previously, we used Tdrd7-deficient mice–which exhibit fully penetrant cataracts and re-capitulate features of the human lens defects–to gain insight into Tdrd7’s role in lens development." (PMID 33665188, 2021). "While Tdrd7 is implicated in the control of key lens mRNAs, the impact of Tdrd7 deficiency on microRNAs (miRNAs) and how this contributes to transcriptome misexpression and to cataracts, is undefined." (PMID 33665188, 2021). "Together, these data uncover TDRD7’s novel upstream role in elevation of stress-responsive chaperones for cytoskeletal maintenance in post-nuclear degradation lens fiber cells, perturbation of which causes early-onset cataracts." (PMID 32420594, 2020). "Hsf4- knockout mice (Hsf4−/−) and Tdrd7-homozygous KO mice (Tdrd7−/−) also cause cataracts." (PMID 33204712, 2020). "TDRD7 regulates the mRNAs critical for lens development, and as a result, Tdrd7 mutant mice develop cataracts." (PMID 37712680, 2023). "We address this critical knowledge-gap by investigating Tdrd7-targeted knockout (Tdrd7-/-) mice that exhibit fully penetrant juvenile cataracts." (PMID 33665188, 2021). "SEM was performed on Tdrd7−/− and control lenses at two different postnatal stages, prior to and after detection of overt cataracts." (PMID 32420594, 2020). "At P28, Tdrd7−/− lens fiber cell membrane protrusions appear to be further malformed, appearing very pleomorphic in comparison with control, which is consistent with the appearance of cataracts." (PMID 32420594, 2020). "Additionally, Hsf4, Tdrd7, gap junction protein epsilon 1 (Gje1), beaded filament structural protein 2 (Bfsp2), and lens intrinsic membrane protein 2 (Lim2) which are also significantly reduced in the SCR lens (<0.5-fold) were linked to human or animal cataracts (Supplement 1)." (PMID 33204712, 2020). "While at P18 there are no obvious lens or eye defects in Tdrd7−/− mice, by P22 cataracts are detected in the knockout animals with 100% penetrance." (PMID 32420594, 2020).
glaucoma (5 papers, 2014 to 2024). Increased pressure in the eyeball due to obstruction of the outflow of aqueous humor. "TDRD7: Loss-of-function mutations in a gene for Tudor domain containing protein 7 (TDRD7) on chromosome 9q were first linked with autosomal recessive cataract and glaucoma." (PMID 38927721, 2024). "Presently, TDRD7, CYP1B1, GJA1, IL1B, MMP1, and MMP3 have been considered as a causative gene for glaucoma." (PMID 33299458, 2020). "In addition, unlike Tap, mouse Tdrd7 is also expressed in somatic tissue - lens fiber cells - and its loss of function results in defects in spermatogenesis and somatic phenotypes such as cataract and glaucoma in mouse and human." (PMID 25287931, 2014). "Mice lacking Tdrd7 develop cataract, glaucoma, and arrested spermatogenesis." (PMID 38927721, 2024).
congenital cataracts (4 papers, 2020 to 2023). "TDRD7 is involved in the development of the lens and the anterior segment, and its mutations could cause congenital cataracts in humans." (PMID 37449273, 2023). "In addition, some researchers have found that the pathogenesis of congenital cataracts caused by TDRD7 deficiency may be related to the immune response, defence response, and related genes LY86, C1QA, C1QB, and C1QC." (PMID 36586009, 2023). "A similar phenotype has been reported in patients with mutations in TDRD7 (tudor domain containing 7), a gene associated a syndrome combining congenital cataracts and non-obstructive azoospermia." (PMID 37034386, 2023).
Age-related cataract (3 papers, 2020 to 2024). A type of cataract (opacification of the lens) that forms during the course of aging. "Furthermore, the mutations of Tdrd7 also cause human congenital and age-related cataracts." (PMID 33204712, 2020). "Eight pairs (protein-coding genes TOM1L2, MXRA7, RHPN2, and HINT1 for senile cataract, WARS1 and TDRD7 for AMD, STAT6 for myopia, and TPPP3 for DR) are newly reported in this study." (PMID 39408566, 2024).
viral infection (3 papers, 2018 to 2023). "To evaluate the relative contribution of Tdrd7 to prevent viral infection and pathogenesis, we generated Tdrd7 conditional knockout mice by crossing floxed (fl)-Tdrd7 (Tdrd7fl/fl) mice with CreCMV deleter mice." (PMID 37712680, 2023). "In summary, Tdrd7 deficiency led to increased AMPK activation and viral infection in primary cells and mice." (PMID 37712680, 2023). "Our results from ex vivo and in vivo studies demonstrated the role of TDRD7/AMPK interaction in protection against viral infection." (PMID 37712680, 2023). "TDRD7 (Tudor Domain-containing 7) is a novel antiviral ISG expressed at low endogenous levels in various cell types and transcriptionally upregulated upon viral infection or IFN treatment." (PMID 34671358, 2021).
colon cancer (1 paper, 2020). "In our study, it was found that TDRD5, TDRD6 and TDRD7 are differentially expressed in CRC, and further studies on the role of these three genes in colon cancer are needed." (PMID 32828126, 2020).
Sjogren syndrome (1 paper, 2021). An autoimmune disorder in which immune cells attack and destroy the glands that produce tears and saliva. "For example, TDRD7 is proven to be a key gene for Sjogren syndrome." (PMID 34305454, 2021).
infection (4 papers, 2014 to 2023). The state of being infected such as from the introduction of a foreign agent such as serum, vaccine, antigenic substance or organism. "This region overlaps several genes, though TDRD7 is potentially the strongest candidate for being linked to the infection status." (PMID 37576560, 2023). "By 14 and 24 days post-infection, Pax6 lentivirus-infected H1 hES cells exhibited expression of γA-crystallin, Prox1, and Tdrd7, similar to expression of the homologous mouse proteins in G4 and Pax6-GFP mES cells." (PMID 25517354, 2014). "Interestingly, Tudor domain-containing 7 (TDRD7) plays the same role in the infection of viruses from the Paramyxoviridae family, including human parainfluenza virus type 3, respiratory syncytial virus, and Sendai virus (SeV)." (PMID 34066434, 2021).
cancer (2 papers, 2020 to 2022). A tumor composed of atypical neoplastic, often pleomorphic cells that invade other tissues. "In summary, the piRNA pathway genes,especially TDRD7, may be potential cancer diagnostic and prognostic biomarkers of ccRCC." (PMID 35273654, 2022). "Some identified prognostic DE RBPs have not been associated with cancers, such as CELF4, POP1, TDRD6, TDRD7, LRRFIP2, and ZC3H12C." (PMID 33224957, 2020).
tumor (2 papers, 2020 to 2022). "High TDRD7 expression was relevant to tumor progression and immune infiltrating cells in patients with ccRCC." (PMID 35273654, 2022). "The results showed that the increase in TDRD7 protein expression was related to tumor stage and tumor grade." (PMID 35273654, 2022). "The Tumor Immune Estimation Resource (TIMER) showed that the mRNA expression level of TDRD7 was positively related to tumor immune infiltrating cells (TICs) in ccRCC." (PMID 35273654, 2022). "The TIMER database showed that the expression level of TDRD7 in ccRCC was positively correlated with the expression levels of tumor immune infiltration cells." (PMID 35273654, 2022). "Together, these results show that TDRD7 might affect tumor proliferation and metastasis and inhibit apoptosis." (PMID 35273654, 2022). "Our results indicated that decreased expression of TDRD7 may be useful in predicting the poor prognosis of patients with ccRCC and may inhibit tumor immune cell infiltration in ccRCC." (PMID 35273654, 2022). "In addition, TDRD7 may play a certain role in the migration of tumour cells." (PMID 32828126, 2020). "We hypothesized that the overexpression of TDRD7 promotes the infiltration of CD8+ T cells and macrophages in ccRCC and ultimately slows tumor progression." (PMID 35273654, 2022).
TDRD7 also shares sentences with these, for which no sentence is quoted: Azoospermia (2 papers); male infertility (1); microphthalmia (1); myopia (1); neurodegenerative disease (1); senile cataract (1); sterility (1).